IFNG (interferon gamma)
Diseases named in the same sentence as IFNG in open-access papers (continued):
Sharing a sentence is not in itself a finding about the gene and the disease.
viral infection (continued). "IL-17-ativated DCs and viral infections trigger natural killer (NK) cells to secret pro-inflammatory cytokines (i.e. TNFα and IFNγ)." (PMID 40673003, 2025). "In mice, CCL3 recruits neutrophil granulocytes to the lung in response to IFNγ-mediated signaling in a virus infection model." (PMID 40111902, 2025). "Only no statistically significant slight enhancements were observed for IL1A, the anti-inflammatory IL10, and the interferon-gamma (IFNG) which increases during a viral infection and in some circumstances, it can act as a pro-inflammatory molecule." (PMID 41573543, 2025). "Incubation of neutrophils with IFNα and IFNγ resulted in gene expression changes that mimicked the cellular defence response to viral infection, whereas IL-1β and TNFα activated genes that are typically involved in the cellular response to bacterial infection." (PMID 41503139, 2025). "The observed loss in Th1 cells, important producers of interferon gamma (IFN-γ), which also plays a significant role in antiviral responses, may have had negative consequences for early antiviral defenses, compromising the host’s ability to control viral infection." (PMID 40331962, 2025). "IFNγ is a crucial immune stimulatory cytokine secreted by various immune cells in response to viral infection." (PMID 40287781, 2025). "Enrichment plots of interferon alpha response and interferon gamma response show significant upregulation in the Huwe1 KD group compared to control group during virus infection." (PMID 39034993, 2024). "In the same line, IFNG protein is a critical player between innate and adaptive immunity after viral infection." (PMID 39470726, 2024). "Its regulation is increased in bacterial infections in response to tumor necrosis factor-alpha, IL-1, and IL-6 and decreased in viral infections by interferon-gamma." (PMID 39724169, 2024). "Our in silico analysis showed a significant relationship with mechanisms of extracellular matrix organization, interferon-gamma activation, and response to viral infections, which must be validated through molecular assays." (PMID 38397053, 2024). "IL-18 plays a role in maintaining the Th1 inflammatory response to viral infection, and it induces the downstream production of IFNG." (PMID 38540716, 2024). "These 34 upregulated genes were enriched for pathways related to the immune response to viral infections, with “cellular response to interferon-gamma” as the most significant pathway (GO:0071346, odds ratio = 74.5, P = 5.22 × 10−15, q value = 2.70 × 10−12)." (PMID 39043677, 2024). "It is elevated in keratinocytes following viral infection, exposure to double-stranded RNA, or IFNγ and IFNβ." (PMID 39399119, 2024). "CD86 gene expression is induced in dendritic cells and Langerhans cells by interferon gamma as well as bacterial and viral infections." (PMID 39302712, 2024). "Gene Ontology (GO) enrichment analysis showed that immune biological processes related to viral infection, such as type I interferon-related pathways and interferon-gamma-related pathways, were significantly enriched among the DEGs." (PMID 39312688, 2024). "NK cells can also respond very early to virus infection, and NK cell IFNγ in the spleen has been reported to respond as early as 12 hours post infection, peaking at approximately 36 hours in the spleen." (PMID 38684766, 2024). "NK cells are important in early control of viral infections and have been shown to produce IFNγ in response to SARS-CoV-2." (PMID 38950078, 2024). "The capsule 19 was involved in RNA splicing, regulation of viral process, cellular response to interferon-gamma, and the antigen processing, indicating that it grouped genes related to the immune responses to viral infection." (PMID 39432561, 2024). "Th1 polarized CD4 T cells express high levels of the transcription factor Tbet and are a major source of IFNγ during viral infection, a cytokine critical for activating innate and adaptive immunity to clear a virus infection." (PMID 38512979, 2024).
viral infection (continued). "During acute viral infection, specific effector cytotoxic T -cells (CTLs) secrete IFNγ, which in turn induce the release of hematopoietic cytokines such as IL-6 from bone marrow-mesenchymal stromal cells (MSCs)." (PMID 38965547, 2024). "The increase of IFNγ in our polymicrobial peritonitis is like that described in viral infections induced by genetic depletion of Ubc9 in myeloid cells." (PMID 37520526, 2023). "Interferon-gamma (IFNγ) is a key cytokine that plays multiple roles in the host immune response to viral infections, for example, influenza A virus (IAV)." (PMID 37842651, 2023). "Previous research has shown that there are sex variations in susceptibility to a viral infection, which are accompanied by a lower CD4+ T cell mediated response, including expression of IFNγ in female mice." (PMID 37169749, 2023). "In line with the JAKi findings from immortalized KC, PHFK treated with ruxolitinib significantly reversed, and fedratinib showed a reproducible trend in reversing, IFNγ-mediated resistance to viral infection." (PMID 37298195, 2023). "To analyze the role of the IFNγ KRKR motif in a virus infection model, we generated a mouse line with the KRKR motif deleted in the endogenous Ifng gene by using CRISPR–Cas9 technology." (PMID 36732425, 2023). "Adaptive immune cells, including CD4 T helper type 1 cells, γδT cells, activated NK cells, and cytotoxic CD8 T cells, secrete IFNγ upon viral infection." (PMID 37264110, 2023). "Our results indicate in two different viral models (VV and HSV-1) that JAK2-selective inhibitors reduce IFNγ-mediated protection from viral infection in KC." (PMID 37298195, 2023). "APOL2, mainly localized at the endoplasmic reticulum, is implicated in cholesterol biosynthesis and trafficking and is thought to mediate cell death induced by interferon-gamma or viral infection, indicating a role in inflammatory processes." (PMID 37055858, 2023). "This phenotype occurs in vivo in response to bacterial or viral infections and is modeled in vitro by exposure to lipopolysaccharide (LPS) or interferon-gamma (IFNγ)." (PMID 37689116, 2023). "IFNγ is traditionally known as a cytokine against viral infections and has anti-tumorigenic activity." (PMID 37199578, 2023). "In contrast to the type I and III interferons produced by any cells upon viral infection, IFNG expression is restricted to specific subsets of immune cells upon infection or stimulation with antigens, but almost all cells can respond to IFNG." (PMID 37052473, 2023). "Interferon gamma is a key factor in viral infections, involved in several immunological pathways, such as antigen processing and presentation, apoptosis, antiviral mediators, lysosome mediated killing/phagosome maturation and complement pathway, among others." (PMID 37112866, 2023). "Like IFNγ, TNFα plays a critical role in the control of viral infections including enhanced antigen presentation, recruitment of leukocytes, apoptosis of infected cells, a direct antiviral effect, and polarization of TH cell responses." (PMID 37866114, 2023). "Whereas Ubc9 depletion increases protective IFNγ responses to viral infections, TAK981 increases TNFα anti-bacterial responses." (PMID 37520526, 2023). "Interferon gamma (IFN-γ) is one of the key interferons to cope with viral infections as it narrows the viral replication by stimulating T lymphocytes for cytokine production along with an activation of the cytotoxic T lymphocytes." (PMID 37756264, 2023). "By inducing multiple downstream interferon-inducible genes and targeting specific viral components, IFNG has shown direct antiviral activity and can target different stage of virus life cycle to inhibit virus infection." (PMID 37052473, 2023). "The only member of the type II IFN family, IFNγ, is essential for the inflammatory response triggered by viral infections." (PMID 37264110, 2023).
viral infection (continued). "Despite PCT synthesis is inhibited by interferon gamma, secreted in viral infections, elevated levels of this biomarker at admission indicate a higher risk of developing a bacterial infection." (PMID 37363332, 2023). "The expression of NOS2 is known to be modulated by IFN-regulatory factor 1 (IRF1); this transcription factor is, indeed, induced by IFNγ during the host immune response to viral infections." (PMID 37893073, 2023). "It is also well-established that the Th1-polarized immune response mediates viral infection control via IFNγ and TNFα cytokine production, ensuring efficient viral clearance." (PMID 37511205, 2023). "IFNγ-mediated resistance to viral infection was reversed by JAK2 inhibition (366 ± 294% increase in infection)." (PMID 37298195, 2023). "In line with the IFNγ-responses, T-cell frequencies measured by dextramer staining were significantly lower after peptide vaccination than after virus infection, both in terms of the WT-specific response and the total dextramer+ T-cell response." (PMID 37573454, 2023). "NK cells, potent IFNγ producers and cytotoxic lymphocytes, are key players in control of viral infection." (PMID 35428875, 2022). "Still, it is essential to consider that interferon-gamma is released during viral infections, including SARS-CoV-2 infection." (PMID 36104051, 2022). "We also observed that the production of IL-10 was rarely seen from cells that were also producing IFNγ in response to HCMV stimulation, which is unusual as dual IL-10 and IFNγ-producing CD8+ T cells are often described in other virus infections." (PMID 36558866, 2022). "In the context of viral infection, NK cells from ebi3-/- and il27Ra-/- mice exhibited significant reductions in IFNγ production during the early phase of IAV infection compared to WT controls." (PMID 35634328, 2022). "IFNγ has been shown to be important in the control of several viral infections, including Ebola and SARS-CoV-2." (PMID 35428875, 2022). "The promotion of IFNγ-producing antigen-specific CD8+ T cells by IL-27 highlights the adjuvant potential of this cytokine for prophylactic measures against viral infection." (PMID 35634328, 2022). "CD8+/CD25+ cells are induced by viral infection and some mechanisms dependent on IL-4 and IL-12, and they regulate Th1/Th2 reactions by production of IL-10 and IFNγ." (PMID 35337377, 2022). "A possible explanation is that viral infections elevate the interferon-gamma (IFN-γ) serum levels, reducing the upregulation of PCT, which justifies the high specificity of PCT for distinguishing viral from bacterial infections." (PMID 35326841, 2022). "Increase in STAT1, during viral infections, by type 1 IFN or IFNγ, have been associated with decreased STAT4 access to receptors." (PMID 36072585, 2022). "IFNG (IFN-γ), one of the major subtypes, is produced by leukocytes and is mainly involved in innate immunity in response to viral infection." (PMID 35401181, 2022). "The interferon alpha and interferon gamma response genes are essential components of the immune response to viral infections." (PMID 35360851, 2022). "In the liver, virus infection induces the expression of IFNα/β, IFNλ genes and IFNγ; however, the contribution of spleen cell systemic IFNγ production is greater as an absolute number than in the liver." (PMID 35456913, 2022). "The “cytokine storm”, an increased release of tumor necrosis factor (TNF), interferon-gamma (IFN-γ), interleukins, and other cytokines, is one of the main characteristics of severe viral infections, including SARS and COVID-19 disease." (PMID 36145270, 2022). "It is well established that priming with IFNγ provides robust protection against virus infection by activating various ISGs." (PMID 35663470, 2022). "A growing body of evidence demonstrates that IL-27 signaling promotes IFNγ production by CD8+ T cells during viral infection." (PMID 35634328, 2022).
viral infection (continued). "Viral infections also induce the production of IFNγ by different cell types that bind with IFNγR of B cells." (PMID 35456913, 2022). "STAT4 is activated by phosphorylation mostly in response to IL-12 and IFN-I and promotes IFNγ production during viral infection." (PMID 35182467, 2022). "During HCV acute infection, NK cells are activated, exhibit direct cytotoxic functions, and secrete interferon-gamma (IFN-γ), thus contributing to the containment of viral infection." (PMID 35891518, 2022). "Accordingly, adoptive transfer of M45-Db CTL protected against in vivo WT virus infection in transgenic B6-SAP-IFNγ mice constitutively producing high serum levels of IFNγ." (PMID 35062332, 2022). "Urothelial expression of CXCL9/10 in response to BKPyV-infection will recruit host immune cells into the tissue, which release IFNγ to start a cascading reaction that limits viral infection." (PMID 35194151, 2022). "Here, we also demonstrated that PBMC from primo-infected individuals after virus infection presented a higher antiviral response including high expression of IFNG, a key to Th1 differentiation and CD8+ T cell activation." (PMID 34571855, 2021). "Aiolos has been recognized as an important regulator of NK cell maturation and function, as it is required for maximal IFNγ secretion and for the full control of viral infection." (PMID 33060840, 2021). "Viral infections can activate NK cells to produce IFNγ, TNFα, and other immunity-enhancing mediators that prime the adaptive immune response." (PMID 35003077, 2021). "Isotype analysis indicated that the rMVAs induced a well-balanced predominantly Th1 type response with IgG2a or IgG2c (depending on the mouse strain) > IgG2b > IgG1 > IgG3, which is the usual order following a viral infection and by IFNγ stimulation." (PMID 33442693, 2021). "IFNγ antiviral properties are complementary to those of type I IFN or are derived from the protective effects of Th1 adaptive responses in many viral diseases studied to date." (PMID 33410731, 2021). "In contrast, cytokines, such as interferon-gamma, which are secreted during a viral infection, lead to down-regulation of PCT assays." (PMID 34583675, 2021). "The production of IFNγ confirmed that the selected epitopes in the VC were able to induce Th1 cells, which are needed for the immune responses against viral infection." (PMID 34960205, 2021). "To better approximate the setting of viral infection, we also treated mice with IFNγ and then measured Eα52-68/I-Ab complex formation." (PMID 34183650, 2021). "NK cells express a repertoire of activating and inhibitory receptors that control NK cell cytotoxicity and interferon-γ (IFNG) production to ensure self-tolerance while allowing efficacy against such insults as viral infection and tumour development." (PMID 33921837, 2021). "Like other viral diseases, the increase in procalcitonin concentrations was only marginal, probably due to the inhibitory effect of cytokines such as interferon gamma." (PMID 33557778, 2021). "This broadens its application range even more—for the treatment of viral infections leading to acute inflammatory conditions characterised by increased cytokine levels, in particular those of IL-6 and IFNγ." (PMID 34639073, 2021). "Isotype analysis indicated that the rMVAs induced a well-balanced predominantly Th1-type response to S with IgG2a or IgG2c (depending on the mouse strain) > IgG2b > IgG1 > IgG3, which is the usual order following a viral infection and by IFNγ stimulation." (PMID 33688035, 2021). "Vitamin A initiates the production of proinflammatory cytokines such as interferon-gamma to resolve viral infection." (PMID 34202697, 2021). "On the other hand, RIG-1 negatively correlated with IFNγ, a necessary cytokine for driving Th1 cell-mediated immunity to control viral infections." (PMID 34211465, 2021).
viral infection (continued). "Interferon-gamma is one of the most important cytokines required to increase CD8+ lymphocyte abundance during viral infection and regulate their homeostasis." (PMID 34025935, 2021). "Interferon-gamma (IFN-γ) expression is induced in response to viral infection and is critical for immunity against viral and bacterial infections." (PMID 33251497, 2020). "This occurs through the increased expression of cytokines, such as IFNγ (Interferon gamma) and TNFα (Tumor necrosis factor alpha), which are typically protective in the context of bacterial and viral infection." (PMID 32708830, 2020). "The JAK-STAT pathway is also central for mounting a host response to viral infection, and treatment with interferon gamma induces the expression of interferon-stimulated genes in EVT cells." (PMID 32974340, 2020). "m6A RNA methylation has been shown to play important roles in the interferon response to viral infections but, to our knowledge, this is the first study showing an increase in the overall levels of m6A in the presence of IFNγ in intestinal cells." (PMID 34968289, 2020). "This is in accordance with recent findings since IFNG-AS1 is transcribed antisense to IFNG, activating IFN-γ production, and the cellular response to viral infections by working as a chromatin structure modifier." (PMID 32214045, 2020). "Serum levels of interleukin-6, interleukin-8, tumor necrosis factor-α, interferon gamma, and granulocyte colony stimulating factor increase following viral infection." (PMID 33425271, 2020). "This is in stark contrast to the normal phenotype arising with viral infections, which specifically trigger Th1/Tc1‐driven responses, with increased secretion of IFNγ and cytotoxic capacity." (PMID 33209300, 2020). "During a viral infection, the immune response is activated and the production and release of pro-inflammatory cytokines, TNFα, IL-1, IL-6 and interferon-gamma (IFNγ) is increased." (PMID 32325767, 2020). "This indicates that IFN-I signaling plays a role in RV16-stimulated IFNγ production by NK cells, and is consistent with previous studies on the role of IFN-I on NK cell IFNγ in other viral infections." (PMID 33194777, 2020). "In response to a bacterial infection, IFNγ directly induces, in 6 hours, nCD64 expression via pSTAT1, whereas in the case of a viral infection, IFNα directly induces, in 8 hours, mCD169 expression via pSTAT1 and pSTAT2." (PMID 32031762, 2020). "The increased IFNG expression suggests that the cultured bovine endometrial cells retained some ability to offer a normal immune response to the viral infection." (PMID 31861316, 2019). "Our work has focussed mainly on type 1 interferons, however, type II interferon (IFNG) also plays an important role in adaptive and innate immunity against both bacterial and viral infections." (PMID 31861316, 2019). "In dengue infection, one study showed that CD4+ T cells that produced either IFNγ or IL-2 correlated with protection from secondary virus infection in children." (PMID 30761131, 2019). "This potent antiviral activity of IFNγ is critical for the control of many CNS-tropic viral infections, such as MV, HSV, SINV, lymphocytic choriomeningitis virus (LCMV), and mouse hepatitis virus (MHV)." (PMID 31514273, 2019). "The elevated levels of the IFNβ suppress the release/production of type II interferon (IFNγ) necessary to clear viral infections." (PMID 30949451, 2019). "IP10/CXCL10 is secreted in response to interferon gamma which is produced as part of the Th1 response to viral infection." (PMID 32116981, 2019). "Microglia expression of IFN-I is stimulated not only directly by virus infection but also indirectly by the pro-inflammatory cytokine IFNγ via the activation of IRF-1." (PMID 30669615, 2019). "Stem cells were either untreated or pre-treated with 20 ng/ml of IFNγ for 24 h administered 1, 2, or 3 days prior to virus infection." (PMID 30917829, 2019).